TSPAN18 (tetraspanin 18)
Description:
Plays a role in the cell surface localization of ORAI1 and may participate in the regulation of Ca(2+) signaling and the VWF release in response to inflammatory stimuli.
Synonyms: TSPAN
Tractability: Antibody: UniProt predicts a signal peptide or a membrane-spanning region; its Gene Ontology location is reachable by antibodies, with medium confidence. PROTAC: its protein half-life has been measured.
Gene: Protein-coding gene on chromosome 11 (44,726,322 to 44,932,427, forward strand). Ensembl gene ENSG00000157570.
Subcellular location: Membrane
Gene Ontology:
Molecular function: protein binding; transmembrane transporter binding
Biological process: calcium-ion regulated exocytosis; calcium-mediated signaling; inflammatory response; protein localization to cell periphery; regulation of sprouting angiogenesis; regulation of store-operated calcium entry
Cellular component: cell periphery; plasma membrane; membrane
Genetic constraint (gnomAD): Loss-of-function variants: 14 observed, 28.02 expected, observed/expected ratio (o/e) 0.5, 90% interval 0.33 to 0.78. The upper end of that interval is the gene's LOEUF score, 0.78, which puts it in group 3 of 6, group 1 being the genes least tolerant of losing a copy. Missense variants: 268 observed, 335.88 expected, observed/expected ratio (o/e) 0.8, 90% interval 0.72 to 0.88. Synonymous variants: 143 observed, 143.03 expected, observed/expected ratio (o/e) 1, 90% interval 0.87 to 1.15.
Homologues: Orthologues: chimpanzee TSPAN18 (100% identical), macaque TSPAN18 (100% identical), pig TSPAN18 (98% identical), dog TSPAN18 (96% identical), guinea pig TSPAN18 (92% identical), mouse Tspan18 (91% identical), rat Tspan18 (90% identical), tropical clawed frog tspan18 (73% identical), zebrafish tspan18b (72% identical), zebrafish tspan18a (68% identical). Paralogues in human: TSPAN1 (32% identical), TSPAN11 (30% identical), TSPAN9 (30% identical), CD151 (29% identical), TSPAN8 (29% identical), TSPAN14 (28% identical), TSPAN17 (28% identical), TSPAN5 (28% identical), CD9 (27% identical), TSPAN4 (27% identical), TSPAN7 (26% identical), CD53 (26% identical), and 20 more.
Diseases named in the same sentence as TSPAN18 in open-access papers:
TSPAN18 is named in the same sentence as 19 diseases in open-access papers, as found by Europe PMC text mining. Sharing a sentence is not in itself a finding about the gene and the disease. The quoted sentences say what the papers report.
schizophrenia (6 papers, 2013 to 2022). A major psychotic disorder characterized by abnormalities in the perception or expression of reality. "A genome-wide association study on schizophrenia in the Han Chinese population implicated three single-nucleotide polymorphisms in the 5′ untranslated region of Tspan18." (PMID 32447449, 2020). "The tetraspanin associated with plasma aβ in this investigation, TSPAN18, has been inconsistently associated with schizophrenia in Han Chinese, while other tetraspanins have been associated with schizophrenia, bipolar disorder, and X-linked mental retardation." (PMID 28704393, 2017). "By contrast, neither genotypic nor allelic modeling revealed significant association between increased schizophrenia risk and the other two TSPAN18 SNPs, rs11038167 or rs11038172." (PMID 23505562, 2013). "A recent genome-wide association study (GWAS) of Han Chinese identified three single-nucleotide polymorphisms (SNPs rs11038167, rs11038172, and rs835784) in the tetraspanins gene TSPAN18 as possible susceptibility loci for schizophrenia." (PMID 23505562, 2013). "Alternatively, Tspan18 on microglial cells could impact on their capacity to mediate synaptic pruning, an excess of which was recently linked to schizophrenia." (PMID 32447449, 2020). "Tetraspanin-18 (TSPAN18) potentially plays a role in the calcium signaling that is associated with dopamine-induced cortical neuron apoptosis and is considered to be an important mechanism in the pathogenesis of schizophrenia (SCZ)." (PMID 26016498, 2015). "Polymorphisms in TSPAN18 have been associated with schizophrenia, but these associations have not been consistently replicated." (PMID 33802509, 2021). "Our findings indicate that the TSPAN18 gene is unlikely to be a major susceptibility gene for schizophrenia in Han Chinese." (PMID 26016498, 2015). "Nevertheless, altered Tspan18 expression in brain endothelial cell or other brain cell types could affect Orai1/Ca2+ signaling and impact brain function and neurological disorders such as schizophrenia." (PMID 32447449, 2020).
benign prostatic hyperplasia (1 paper, 2023). A non-cancerous nodular enlargement of the prostate gland. "TSPAN18 was highly expressed in PCa tissues compared to adjacent benign prostatic hyperplasia (BPH) tissues." (PMID 37542345, 2023).
deep vein thrombosis (1 paper, 2020). "As a consequence, Tspan18-knockout mice are protected in ischemia–reperfusion and deep vein thrombosis models." (PMID 32447449, 2020). "However, the Tspan18-knockout mice display endothelial defects that yield partial protection in two thrombo-inflammatory models: a deep vein thrombosis model (60% reduction in thrombus size) and an ischemia–reperfusion injury heart attack model (50% reduced platelet deposition)." (PMID 32447449, 2020).
glioma (1 paper, 2023). A benign or malignant brain and spinal cord tumor that arises from glial cells (astrocytes, oligodendrocytes, ependymal cells). "Meanwhile, TSPAN18 has good predictive performance for the 1-, 3-, and 5-year survival rates of patients with glioma." (PMID 37587203, 2023).
tumor (7 papers, 2019 to 2024). "Here, we found that TSPAN18 was an upstream regulator of STIM1-mediated Ca2+ signaling pathway, and was mainly overexpressed in tumor cells and associated with worse prognosis in PCa." (PMID 37542345, 2023). "In comparison, tetraspanin 12 (Tspan12, a paralogue of Tspan18), recently shown to be expressed in retinal vessels, was widely expressed in embryonic tissues as well as human tumor cell lines." (PMID 32694189, 2021). "Overall, targeting TSPAN18 might severed as a novel and more tumor cell-specific therapeutic target for bone metastasis of PCa." (PMID 37542345, 2023). "Next, we divided the PCa patients into two groups based on TSPAN18 expression in tumor tissue." (PMID 37542345, 2023). "Moreover, xenograft tumor models and clinical specimens further identified the oncogenic role of TSPAN18 mediated by its positive regulation of STIM1." (PMID 37542345, 2023). "Furthermore, we observed that tumor TSPAN18 expression was significantly associated with advanced Gleason score and bone metastasis, but not T stage in both cohorts, suggesting that TSPAN18 was crucial for promoting tumor metastasis." (PMID 37542345, 2023). "The MTT assay and xenograft tumor mouse model demonstrated that neither knockdown nor overexpression of TSPAN18 affected proliferation of PCa cells in vivo or in vitro." (PMID 37542345, 2023).
cancer (6 papers, 2021 to 2025). A tumor composed of atypical neoplastic, often pleomorphic cells that invade other tissues. "Kaplan-Meier analysis also demonstrated that high TSPAN18 expression was significantly associated with decreased overall survival (OS) and cancer specific survival (CSS) in both cohorts." (PMID 37542345, 2023). "Given the critical role of STIM1 in activating the Ca2+ signaling pathway in cancer cells and the positive role of TSPAN18 in regulating STIM1, we tested the effect of TSPAN18 on the Ca2+ signaling pathway." (PMID 37542345, 2023). "Furthermore, transcriptome sequencing and gene ontology (GO) analysis revealed that the Ca2+ signaling pathway is one of the most enriched cancer-related pathways in TSPAN18 knockdown cells." (PMID 37542345, 2023). "These cancer cell lines may have contextual mismatch in understanding if Tspan18 targets VEGF or Notch pathway or both using endothelial cells deficient in VEGFRs or Notch receptors." (PMID 32694189, 2021).
neurological disorders (1 paper, 2020). "For instance, Tspan18 on endothelial cells could be important for brain function, since endothelial dysfunction in the brain and inflammation is linked to neurological disorders." (PMID 32447449, 2020).
TSPAN18 also shares sentences with these, for which no sentence is quoted: type 2 diabetes (3 papers); gastric cancer (2); hepatocellular carcinoma (2); bipolar disorder (1); Cognitive impairment (1); developmental delay (1); hypopituitarism (1); intestinal cancer (1); liver cancer (1); melanoma (1); Obesity (1); prostate carcinoma (1).